MMD (monocyte to macrophage differentiation associated)
Description:
Involved in the dynamics of lysosomal membranes associated with microglial activation following brain lesion.
Synonyms: PAQR11; MMA; MMD1
Tractability: Antibody: its Gene Ontology location is reachable by antibodies, with high confidence; UniProt predicts a signal peptide or a membrane-spanning region. PROTAC: its protein half-life has been measured.
Gene: Protein-coding gene on chromosome 17 (55,392,616 to 55,421,944, reverse strand). Ensembl gene ENSG00000108960.
Subcellular location: Late endosome membrane; Lysosome membrane
Subcellular location (Human Protein Atlas): Vesicles
Gene Ontology:
Molecular function: protein binding; protein kinase activity; signaling receptor activity; pore-forming activity
Biological process: positive regulation of neuron differentiation; positive regulation of protein kinase activity; regulation of protein localization
Cellular component: Golgi apparatus; membrane; plasma membrane; late endosome membrane; lysosomal membrane
Genetic constraint (gnomAD): Loss-of-function variants: 18 observed, 20.67 expected, observed/expected ratio (o/e) 0.87, 90% interval 0.6 to 1.29. The upper end of that interval is the gene's LOEUF score, 1.29, which puts it in group 5 of 6, group 1 being the genes least tolerant of losing a copy. Missense variants: 201 observed, 233.34 expected, observed/expected ratio (o/e) 0.86, 90% interval 0.77 to 0.97. Synonymous variants: 79 observed, 74.98 expected, observed/expected ratio (o/e) 1.05, 90% interval 0.88 to 1.27.
Homologues: Orthologues: macaque MMD (100% identical), dog MMD (99% identical), mouse Mmd (99% identical), pig MMD (99% identical), rat Mmd (99% identical), chimpanzee MMD (97% identical), guinea pig MMD (96% identical), tropical clawed frog mmd (88% identical), zebrafish mmd (80% identical), rabbit MMD (78% identical), Drosophila melanogaster AdipoR (18% identical), Caenorhabditis elegans paqr-1 (17% identical), and 1 more. Paralogues in human: MMD2 (71% identical), PAQR5 (20% identical), ADIPOR1 (18% identical), ADIPOR2 (18% identical), PAQR6 (17% identical), PAQR4 (16% identical), PAQR8 (16% identical), PAQR7 (14% identical), PAQR3 (14% identical), PAQR9 (13% identical).
Diseases named in the same sentence as MMD in open-access papers:
MMD is named in the same sentence as 17 diseases in open-access papers, as found by Europe PMC text mining. Sharing a sentence is not in itself a finding about the gene and the disease. The quoted sentences say what the papers report.
lung carcinoma (4 papers, 2015 to 2024). "MMD, a gene associated with differentiation of monocytes into macrophages, is a key signature of a relapse and survival among patients and is involved in lung cancer." (PMID 26179909, 2015). "The knockdown of MMD promoted cell cycle arrest and inhibited the growth of A549 and LLC lung cancer cell lines." (PMID 33101281, 2020). "Emerging reports showed that MMD, CBX7, FAP played an important role in the proliferation of lung cancer." (PMID 26870998, 2016).
lung adenocarcinoma (3 papers, 2022 to 2024). A carcinoma that arises from the lung and is characterized by the presence of malignant glandular epithelial cells.
Diabetes (1 paper, 2024). "The downregulation of MMD was predominantly enriched in pathways associated with Maturity Onset Diabetes of the Young, Primary Immunodeficiency, Glycosphingolipid Biosynthesis - Lacto- and Neolacto-series, Phototransduction, and Hypertrophic Cardiomyopathy." (PMID 39735537, 2024).
External ophthalmoplegia (1 paper, 2007). Paralysis of the external ocular muscles. "However, MmD-associated mutations give rise to clinical features such as external ophthalmoplegia, bulbar involvement and a moderate degree of respiratory impairment which are not commonly observed in typical CCD." (PMID 17504518, 2007).
gastric cancer (1 paper, 2025). A primary or metastatic malignant neoplasm involving the stomach. "We confirmed MMD expression in GC and its impact on gastric cancer development." (PMID 40308510, 2025). "The findings indicated that reducing MMD expression in the group resulted in a notable decrease in the cell proliferation rate compared to the NC group in AGS and SNU-216, suggesting that inhibiting MMD expression could slow down the growth of gastric cancer cells." (PMID 40308510, 2025).
keratoconus (1 paper, 2023). A degenerative, structural disorder of the eye, characterized by a cone-shaped protrusion of the cornea. "We overlaid these 4 modules with FRGs and found that 8 FRGs (LCE2C, NOS2, AKR1C3, CAV1, MMD, LINC00618, SNCA, SLC7A11) were closely related to the disease state of keratoconus." (PMID 37626095, 2023).
kidney stones (1 paper, 2020). "Based on the results of the data set analysis, PTGS1, GPX3 and MMD were also highly expressed in the samples of kidney stones." (PMID 33277533, 2020). "Some previous studies have shown that LCN2, PTGS1, GPX3 and MMD may play a role in the development and progression of kidney stones." (PMID 33277533, 2020).
metabolic syndrome (1 paper, 2024). A cluster of metabolic risk factors for CARDIOVASCULAR DISEASES and TYPE 2 DIABETES MELLITUS. "Moreover, blueberry supplementation has been shown to decrease monocyte expression of monocyte-to-macrophage differentiation-associated (MMD) and C-C motif chemokine receptor 2 (CCR2), reducing inflammation in metabolic syndrome patients." (PMID 38558823, 2024).
osteosarcoma (1 paper, 2023). A usually aggressive malignant bone-forming mesenchymal neoplasm, predominantly affecting adolescents and young adults. "Combining literature reports and our results of bioinformatics and RT-qPCR, we hold that EPHX2 and FDPS are the oncogenes, while GBP1, MMD and ZYX are the anti-oncogene in osteosarcoma." (PMID 37090691, 2023).
cancer (5 papers, 2015 to 2025). A tumor composed of atypical neoplastic, often pleomorphic cells that invade other tissues. "Although function of the MMD protein is unknown, certain studies have shown that macrophage activation promotes cancer metastasis." (PMID 26179909, 2015).
tumor (4 papers, 2022 to 2025). "Hence, the results indicated that MMD knockdown slowed tumor growth in vivo caused by MKN-45." (PMID 40308510, 2025).
infection (1 paper, 2022). The state of being infected such as from the introduction of a foreign agent such as serum, vaccine, antigenic substance or organism. "The results showed that overexpression of circMGAT5 significantly promoted MMD expression at 24 h post-infection, while interference with circMGAT5 significantly inhibited the expression of MMD." (PMID 36458003, 2022). "The results showed that miR-132c-5p mimic could significantly inhibit expression of the MMD gene during infection, while miR-132c-5p inhibitor slightly promoted MMD expression, although not at a significant level." (PMID 36458003, 2022). "Expression of the MMD gene was detected 24 h after infection with E. tenella sporozoites." (PMID 36458003, 2022).
MMD also shares sentences with these, for which no sentence is quoted: Crohn disease (1 paper); hypertrophic cardiomyopathy (1); melanoma (1); Primary Immunodeficiency (1); thyroid cancer (1).